TRIM46 (tripartite motif containing 46)
Diseases named in the same sentence as TRIM46 in open-access papers (continued):
Sharing a sentence is not in itself a finding about the gene and the disease.
endometrial cancer (1 paper, 2019). Primary or metastatic malignant neoplasm involving the endometrium (mucous membrane that lines the endometrial cavity). "Among these survival-related genes, five genes (EPHB2, FBP1, NLRC3, PPP2R3A, and TRIM46) were included in a previously reported 9-gene signature for predicting endometrial cancer patient survival." (PMID 30847026, 2019).
gastric cancer (1 paper, 2021). A primary or metastatic malignant neoplasm involving the stomach. "Numerous previous evidence showed the association between MUC1 and the carcinogenesis of various tumor including gastric cancer; however, there was no expression of TRIM46 in the gastric mucosa." (PMID 34532288, 2021).
Opportunistic infection (1 paper, 2022). An infection that is caused by a pathogen that would generally not be able to cause an infection in a host with a normal immune system. "Another commonly observed opportunistic infection is caused by Clostridium difficile toxin B (TcdB); one of its main virulence factors was reported to induce an inflammatory response in the colon via the TRIM46/DUSP1/MAPKs pathway, and TRIM46 deficiency can restrict colon inflammation." (PMID 35373402, 2022).
renal failure (1 paper, 2024). "Serum Mg2+ levels were associated with MUC1/TRIM46 (p = 2.9 × 10−7), SHROOM3 (p = 4.0 × 10−7), and SLC22A7 (p = 1.0 × 10−6) at nominal significance, which is in combination with the eQTL data suggesting that they are possible candidates for renal failure." (PMID 38279093, 2024).
small cell lung carcinoma (1 paper, 2019). Small cell lung cancer (SCLC) is a highly aggressive malignant neoplasm, accounting for 10-15% of lung cancer cases, characterized byrapid growth, and early metastasis. "Furthermore, anti-TRIM46 antibodies have been found in patients with diverse neurological syndromes and are associated with small-cell lung carcinoma." (PMID 32117427, 2019).
type 2 diabetes (1 paper, 2024). "Our results suggest that genetic variation in or near TAF3, MUC1/TRIM46, SHROOM3, and SLC22A7 are associated with the regulation of serum Mg2+ concentrations which may be partially explained by renal function, in type 2 diabetes." (PMID 38279093, 2024). "In conclusion, serum magnesium concentrations are associated with genetic variability around the regions of TAF3, MUC1/TRIM46, SHROOM3, and SLC22A7 in type 2 diabetes." (PMID 38279093, 2024).
viral infection (1 paper, 2022). "Thus, this study revealed novel activities of TRIM46 in innate immunity, which potentiates the study of innate immunity against virus infection." (PMID 36329446, 2022).
cancer (9 papers, 2015 to 2025). A tumor composed of atypical neoplastic, often pleomorphic cells that invade other tissues. "EMT, a key process in cancer metastasis, was examined for its association with TRIM46." (PMID 39937005, 2025). "By targeting components of the β-catenin destruction complex, TRIM46 likely facilitates β-catenin stabilization and activation, thereby driving EMT-associated gene expression and enhancing cancer cell invasiveness." (PMID 39937005, 2025). "Silencing of TRIM46 suppressed cancer cell invasion stimulated by OC-MQ and mesenchymal marker expression without affecting cell viability." (PMID 39937005, 2025). "Among most significantly altered genes, we selected FGF2, LY6L, and TRIM46 for further study because their gene products are known to increase the viability and malignant proliferation of cancer cells." (PMID 38600695, 2024). "Despite the involvement of some of functional partners of TRIM46 in the cancer process, reports of a link between these genes and ccRCC are lacking." (PMID 34881275, 2021). "Although TRIM46 has demonstrated its potential as a biomarker in cancers, its clinical value and specific effects on the occurrence and progression of ccRCC remained largely unclear." (PMID 34881275, 2021). "Furthermore, treatment with MQ-CM or cancer-stimulated macrophage CM (OC-MQ-CM) significantly increased TRIM46 protein expression." (PMID 39937005, 2025). "Notably, the suppression of TRIM46 expression substantially reduced OC-MQ-facilitated cancer cell invasion." (PMID 39937005, 2025). "Notably, PTPN1, TRIM46, TRIM17, FCGR1A, IRF5, IRF6, and CAMK2B had a higher frequency of gain mutations in most human cancer types." (PMID 37941546, 2023). "Therefore, more studies of other TRIM46 targets that promote cancer growth are needed in this area." (PMID 35354796, 2022). "Thus, Trim46 might a novel target for cancer therapy, which needed to be validated in more cell lines with different cancer types in future studies." (PMID 27110773, 2016). "The presence of this fusion transcript in TCGA cancer samples is supported by 25 paired “chimeric” reads with one read mapping to MUC1 and the other to TRIM46 (using GRCh37/hg19)." (PMID 26492273, 2015). "Trim46 belongs to a large gene family with a tripartite motif (Trim) that consists of three zinc-binding domains, a RING, a B-box type 1 and a B-box type 2, and a coiled-coil region, and most of the family members are involved in cancer and development." (PMID 27110773, 2016). "By analyzing the mRNA-seq reads from The Cancer Genome Atlas (TCGA), we uncovered a novel cancer-enriched chimeric RNA as the result of splicing between MUC1, a highly glycosylated transmembrane mucin, TRIM46, a tripartite motif containing protein, and KRTCAP2, a keratinocyte associated protein." (PMID 26492273, 2015). "Importantly, silencing TRIM46 did not affect the cell viability of the cancer cells." (PMID 39937005, 2025). "Genes located above TRIM46 in the heatmap, such as ALOXE3, NR4A3, and TMEM88, did not exhibit similar upregulation in advanced-stage cancer tissues." (PMID 39937005, 2025).
tumor (9 papers, 2015 to 2025). "Mechanically, TRIM46 displayed regulatory functions in ccRCC progression via several tumor-associated pathways." (PMID 34881275, 2021). "We estimated the association between TRIM46 with tumor immunity in ccRCC." (PMID 34881275, 2021). "Moreover, the association of TRIM46 and tumor immunity was equally uncovered in this study." (PMID 34881275, 2021). "PPARγ is a critical regulator in tumor progression, and its expression is modulated by factors such as miR-27b and TRIM46, which in turn influence its impact on diseases like OS." (PMID 40370434, 2025). "The findings indicated that TRIM46 amplification promoted tumor growth and enhanced its DDP resistance." (PMID 35354796, 2022). "TUNEL staining of tumor tissues revealed that TRIM46 amplification significantly suppressed apoptosis and DDP-induced apoptosis of tumor cells." (PMID 35354796, 2022). "TRIM46 amplification not only increased tumor growth and tumor sizes, but also ameliorated DDP-caused decrease of tumor growth and tumor sizes." (PMID 35354796, 2022). "Silencing of TRIM46 significantly inhibited the growth of H358 and H1299 cells in vitro and tumor growth in vivo." (PMID 35354796, 2022). "TRIM46 expression was shown to be positively correlated with tumor size, TMN stage, and lymphnode metastasis." (PMID 35354796, 2022). "In breast cancer, TRIM46 acts as a positive regulator in the proliferation and migration of tumor cells." (PMID 34881275, 2021). "A nomogram based on TRIM46 expressions and other independent prognostic factors could robustly predict the overall survival of tumor patients." (PMID 34881275, 2021). "Additionally, the elevated expression level of TRIM46 was an independent prognostic factor for poor OS in patients with ccRCC, indicating that TRIM46 may serve as a tumor promotor of ccRCC." (PMID 34881275, 2021). "The three most significant signaling pathways are valine, leucine, and isoleucine degradation; fatty acid degradation; and glycerophospholipid metabolism, suggesting TRIM46 might affect the metabolism of substances in tumor cells and thus be involved in ccRCC progression." (PMID 34881275, 2021). "Besides, we observed that TRIM46 was distinctly related to tumor immunity in ccRCC." (PMID 34881275, 2021). "Comparing tumor size, TNM stage, and lymphnode metastasis between TRIM46 high- and low expressing tumors, we found that TRIM46 expression positively correlated to sizes of tumor, TMN stages, and metastasis." (PMID 35354796, 2022). "Data also indicated that TRIM46 was an independent predictor of LUAD aggressiveness and tumor sizes with significant hazard ratio (HR)." (PMID 35354796, 2022). "Next, tumor tissues with or without TRIM46 amplification were used to generate a PDX model, and DDP was administered." (PMID 35354796, 2022). "Secondly, the expression of TRIM46 at protein levels in tumor specimens was not reported, which was needed to be further demonstrated." (PMID 34881275, 2021).
infection (1 paper, 2022). The state of being infected such as from the introduction of a foreign agent such as serum, vaccine, antigenic substance or organism. "The results showed that H7N9 virus induced the TRIM46 protein at different times, reaching a peak at 48 h post infection (h.p.i)." (PMID 36329446, 2022).
TRIM46 also shares sentences with these, for which no sentence is quoted: hyperuricemia (2 papers); cerebellar degeneration (1); influenza (1); meningoencephalitis (1); neurodevelopmental disorder (1); osteoporosis (1).